NDRG4 (NDRG family member 4)
Diseases named in the same sentence as NDRG4 in open-access papers (continued):
Sharing a sentence is not in itself a finding about the gene and the disease.
tumor (continued). "A previous study suggested that the NDRG4 gene is present in CRC tumor tissues and bodily fluids with high stability and repeatability." (PMID 25663916, 2015). "NDRG4 has been investigated as a possible tumor suppressor, and NDRG4 mRNA and protein expression were found to be lower in CRC than in control samples, which was observed to correlate with the methylation status of the promoters of this gene." (PMID 25202404, 2014). "Given that cell adhesion is the basis for cell mobility and spreading, we next investigated whether NDRG4 silencing impacted in vitro tumor cell haptotactic migration towards ECM ligands." (PMID 30963110, 2019). "As a result, we found that reduced NDRG4 mRNA expression was associated with tumor progression, as well as unfavorable outcome independent of patients' clinical features and molecular variables including KRAS, BRAF and PIK3CA mutations and MSI status." (PMID 26515606, 2016). "Patients with tumor of reduced NDRG4 mRNA level had unfavorable disease-free and overall survival." (PMID 26515606, 2016). "Meanwhile, accumulated evidences showed that NDRG4 possess tumor-suppressive and oncogenic functions depending on the tissue type, and might be a potential biomarker for predicting aggressive forms of cancer." (PMID 27175791, 2016). "For this purpose, we firstly transfected pCMV6-NDRG4 into tumor cells, which was proved to could increase NDRG4 expression." (PMID 25749388, 2015). "NDRG4 plays varied roles in tumor suppression and progression in various cancers." (PMID 26053091, 2015). "This could be possibly attributed to the aberrant regulation of PI3K-AKT activity by NDRG4, which accommodated tumor malignant biological behavior and subsequently attenuated the prognostic role of NDRG4." (PMID 25749388, 2015). "Our study also showed for the first time that NDRG4 may play its tumor suppressive role through attenuation of PI3K-AKT activity." (PMID 25749388, 2015). "Additionally, NDRG4, a gene known for its role in mediating cellular stress responses, was also upregulated, suggesting a complex interplay between oncogenic signaling and stress adaptation within the tumor microenvironment." (PMID 40950184, 2025). "N-myc downstream-regulated gene 4 (NDRG4) belongs to the NDRG family, the members of which are expressed in a variety of human organs, and are associated with a wide range of biological processes, such as organ development, tumor inhibition, angiogenesis, and growth regulation." (PMID 35893690, 2022). "We speculated that NDRG4 might play its tumor suppressive role through suppression of PI3K-AKT." (PMID 25749388, 2015). "In addition, our results could also provide important clues in understanding how the PI3K-AKT signal is regulated by Myc and NDRG4 in tumor carcinogenesis and progression." (PMID 25749388, 2015). "Of note, the reconstitution of NDRG4 in EAC cells significantly inhibited tumor cell growth and cell proliferation, suggesting a tumor suppressor role in EAC." (PMID 32927604, 2020). "NDRG4 and SDC2 had higher frequency and level of methylation in tumors than in normal or non-tumor adjacent tissues." (PMID 31602277, 2019). "Although NDRG4 shares about 60% amino acid sequence homology with NDRG2, different from the widely tumor suppressive role of NDRG2, NDRG4 has been considered to be expressed mainly in brain and heart, and take part in the development of these organs." (PMID 26515606, 2016). "In this study, we demonstrated that SEPT9, NDRG4, and SDC2 had higher frequency and level of methylation in tumors than in normal or non-tumor adjacent CRC tissues, indicating that these methylated genes may have diagnostic potential for CRC screening." (PMID 31602277, 2019). "To confirm this inhibitory effect of NDRG4 on PI3K-AKT activity, we firstly examined whether transfection of pCMV6-NDRG4 could increase NDRG4 expression in tumor cells." (PMID 25749388, 2015). "NDRG4 is a member of the NDRG gene family and is a known tumor suppressor gene." (PMID 25663916, 2015).
tumor (continued). "However, to our knowledge, the protein expression of NDRG4 and its role in tumor carcinogenesis, progression and prognosis has not been addressed yet." (PMID 25749388, 2015). "While tumors with positive p-AKT staining showed significant poor survival among NDRG4 negative ones, indicating the activation of PI3K-AKT activity without potential NDRG4 suppression might aggravated tumor malignant biological behavior and subsequent prognosis." (PMID 25749388, 2015). "The methylation status of SEPT9, BMP3, NDRG4, and SDC2 was analyzed by using qMSP in matched patient tissue samples (n=23) from tumor, non-tumor adjacent tissue, and normal tissue." (PMID 31602277, 2019).
cancer (16 papers, 2015 to 2025). A tumor composed of atypical neoplastic, often pleomorphic cells that invade other tissues. "For example, oncogenes like PCAT-1, MALAT1, and NDRG4 which associated with progression in pan-cancer had also been identified as prognostic biomarkers in CRC." (PMID 33203797, 2020). "As the NDRG4 gene regulates the proliferation of cancer-associated cells, we performed gain- and loss-of-function studies to examine whether NDRG4 has the same roles in myoblast proliferation." (PMID 29254199, 2017). "However, the research of NDRG4 variants in human cancers is scarce." (PMID 28042954, 2017). "Northern and dot blot analysis demonstrated that NDRG2, NDRG3, and NDRG4 are highly expressed in adult human brain and almost undetectable in eight human cancer cell lines (HL-60, HeLa S3, K-562, MOLT-4, Raji, Daudi, SW480, and A549)." (PMID 40378957, 2025). "NDRG4 has been negatively correlated with outcomes in different cancer types, and its methylation has served as a biomarker in colorectal and gastric cancer." (PMID 38611020, 2024). "The role of NDRG4 in human cancers is quite controversial, in particular in tumors of the central nervous system." (PMID 32927604, 2020). "The study of NDRG4 and cancer is gaining more and more attention, although discrepant results have been observed." (PMID 28042954, 2017). "The positive rate of methylated NDRG4 gene expression was 81% (68/84) in carcinoma tissues, while the positive rate was only 8.3% (7/84) in paracarcinoma tissues." (PMID 25663916, 2015). "The positive detection rate of methylated NDRG4 was 81% in carcinoma tissue, 8.3% in paracarcinoma tissues, 54.8% in blood, 72.6% in urine and 76.2% in stools." (PMID 25663916, 2015). "There was a significant difference in the levels of methylated NDRG4 in carcinoma as compared with the paracarcinoma tissues (P<0.01)." (PMID 25663916, 2015). "nMSP detection was successfully used to assess for methylated NDRG4 in carcinoma and paracarcinoma tissues, feces, urine and blood of the 84 CRC cases." (PMID 25663916, 2015). "Ndrg4 belongs to the NDRG (N-myc Downstream-Regulated Gene) family, which includes four related members, known to be important in tumorigenesis and linked to a range of cancers." (PMID 27902705, 2016). "However, considering that NDRG4 is exclusively expressed in neurons, it is debatable whether NDRG4 would be of major influence in a glia-originated cancer." (PMID 31485792, 2019). "Evidence provided indicated that miR-139-5p and miR-483-5p target N-Myc downstream-regulated gene 4 (NDRG4) and NDRG2, respectively, and that overexpression of either NDRG4 or NDRG2 inhibits the invasive capacity of cancer cells." (PMID 33435156, 2021). "Analyses of TCGA (The Cancer Genome Atlas) and GEO (Gene Expression Omnibus) data sets and EAC tissue samples demonstrated that NDRG4 was significantly downregulated in EAC (p < 0.05)." (PMID 32927604, 2020). "We have previously demonstrated that NDRG4 can significantly inhibit PI3K-AKT activity which has been considered to be involved in the pathogenetic link between excess energy balance and cancer." (PMID 26515606, 2016). "NDRG4 and NDRG2 have also been regarded to exhibit the tumor suppressive function by inhibiting cell proliferation, migration, invasion, and metastasis in different types of cancer, such as glioblastoma and breast cancer." (PMID 33435156, 2021).
gastrointestinal tumors (1 paper, 2020). "Our data, showing its downregulation in EAC, support the evidence that NDRG4 behaves differently in gastrointestinal tumors." (PMID 32927604, 2020).
NDRG4 also shares sentences with these, for which no sentence is quoted: cognitive deficits (2 papers); infection (2); adenocarcinoma (1); benign tumor (1); bladder cancer (1); colorectal (1); colorectal adenoma (1); lung carcinoma (1); myocardial infarction (1); Tetralogy of Fallot (1); ulcerative colitis (1); ventricular septal defect (1); α thalassemia (1).